BMAL1 (basic helix-loop-helix ARNT like 1)
Diseases named in the same sentence as BMAL1 in open-access papers (continued):
Sharing a sentence is not in itself a finding about the gene and the disease.
Hyperglycemia (19 papers, 2013 to 2026). An increased concentration of glucose in the blood. "Embryonic Bmal1 KO models develop insulin deficiency, hyperglycemia, and glucose intolerance as adults, indicating that BMAL1 is critical for the function and metabolic set point programming of pancreatic β-cells." (PMID 41522721, 2026). "Bmal1-deficient diabetic rats suffered from circadian rhythm disturbance, β-cell secretion abnormality, hyperglycemia, and impaired glucose tolerance." (PMID 36838862, 2023). "Mice with both Clock gene mutation and Bmal1 deletion showed impaired glucose homeostasis with hyperglycemia and hypoinsulinemia." (PMID 32365676, 2020). "Loss of Bmal1 in mice has been shown to cause hyperglycemia due to impairment in β-cells function while deletion of Noc in mice causes higher fasting glucose." (PMID 23922759, 2013). "It is, therefore, suggested that CLPr-caused down-regulation of Bmal1 may be involved in amelioration of postprandial hyperglycemia." (PMID 32801469, 2020). "Selective inactivation of Bmal1 in the pancreas or in the β cells causes hyperglycemia due to impaired insulin secretion, and isolated pancreatic islets from adult mice display circadian oscillation in glucose-stimulated insulin secretion which is abrogated by Bmal1 ablation." (PMID 27752300, 2016). "Critically, functional linkage is demonstrated by the ability of BMAL1 overexpression to protect cardiomyocytes from hyperglycemia-induced damage; it achieves this by blocking the mTOR pathway, thereby reversing hyperglycemia-induced autophagy suppression." (PMID 41234362, 2025). "BMAL1 knockout mice show circadian rhythm disorder, β cell secretion disorder, hyperglycaemia, and impaired glucose tolerance and ultimately develop diabetes." (PMID 33414413, 2021). "By contrast, mice with pancreatic beta cell-specific Bmal1 deletion (P-Bmal1 KOs) show hyperglycemia and impaired glucose tolerance due to decreased insulin exocytosis." (PMID 28243224, 2017). "Similar to pancreas-specific loss of BMAL1, we observed significant hyperglycemia without a concomitant increase in insulin, and PdxCre;Clockflx/flx mice were glucose intolerant and displayed reduced insulin secretion following a glucose challenge compared with their littermate controls." (PMID 32616519, 2020). "In contrast to the changes seen in mice with Bmal1 deletion in the liver, Pdx1-Cre mice crossed with Bmal1fl/fl mice (to produce mice lacking Bmal1 in pancreatic tissue) show hypoinsulinemia and hyperglycemia following food intake." (PMID 33668705, 2021).
Parkinson disease (19 papers, 2015 to 2026). A progressive degenerative disorder of the central nervous system characterized by loss of dopamine producing neurons in the substantia nigra and the presence of Lewy bodies in the substantia nigra and locus coeruleus. "In humans, circadian misalignment or clock (BMAL1) gene polymorphism has been associated with the occurrence of neurodegenerative diseases such as Alzheimer's and Parkinson's disease." (PMID 40171795, 2025). "Circadian rhythm dysfunction is a hallmark of Parkinson disease (PD), and diminished expression of the core clock gene Bmal1 has been described in patients with PD." (PMID 38032732, 2024). "Patients with early stages of Parkinson’s disease (PD) exhibit arrhythmic expression of circadian genes, impaired blood levels of cortisol and melatonin, impaired sleep quality, and decreased BMAL1 mRNA levels in whole blood white cells, which is associated with the severity of PD symptoms." (PMID 41440117, 2025). "In patients with Parkinson's disease (PD), the baseline levels of relative expression of the Bmal1 gene at approximately 9:00 am are found to be 57% lower than those of the Per1 gene in peripheral blood." (PMID 41243864, 2025). "This has been observed in studies of sleep-deprived mice with Alzheimer’s disease, which showed altered levels of BMAL1 protein, as well as in patients with Parkinson’s disease, in whom relative BMAL1 levels positively correlate with disease severity." (PMID 40700255, 2025). "Neurologically, nobiletin attenuates neurodegeneration in a Parkinson’s disease rat model by enhancing Bmal1 and activating the Bmal1/NRF2 axis, reducing ferroptosis and oxidative stress, and promoting mitophagy/autophagy." (PMID 41155643, 2025). "In a Chinese population, BMAL1 rs900147 and PER1 rs2253820 SNPs were associated with Parkinson’s disease (PD)." (PMID 37761843, 2023). "Studies investigating changes in the molecular clock mechanism have highlighted altered BMAL1 mRNA expression in Parkinson’s patients." (PMID 35000606, 2022). "Because motor phenotypes resemble symptoms observed in neurodegenerative diseases like Parkinson’s and Huntington’s disease, we tested whether dopamine signaling was affected by the conditional Bmal1 knockout." (PMID 35755440, 2022). "In addition to this, 8 main Bmal1-related signaling pathways were identified as Huntington disease, Parkinson disease, ATP synthesis, apoptosis, CCKR signaling, cytoskeletal regulation, glycolysis, and ubiquitin-proteasome pathway." (PMID 31836786, 2019). "It was also reported that the transcription factor Bmal1 may play an important role in neurodegenerative disorders in humans such as Parkinson disease, Huntington disease and Alzheimer disease." (PMID 31836786, 2019). "Furthermore, increased risk of Alzheimer’s disease and Parkinson’s disease has been associated with the incidence of single-nucleotide polymorphisms in CLOCK and BMAL1, and in BMAL1 and PER1, respectively." (PMID 31293431, 2019). "In contrast, astrocyte- or microglia-specific BMAL1 deletion does not induce dopaminergic neuron loss, though BMAL1’s role in these glial cells influences redox balance and gliosis, which are relevant to Alzheimer’s and Parkinson’s pathology." (PMID 41522721, 2026). "In a 6-OHDA (6-hydroxydopamine)-induced Parkinson’s disease cell model, dihydroisotanshinone I, a compound derived from Danshen (Salvia miltiorrhiza), attenuated cell death, suppressed ROS and caspase-3 activity, and increased SIRT1 expression while reducing BMAL1 levels and apoptosis." (PMID 41440117, 2025).
Alzheimer disease (18 papers, 2015 to 2025). A progressive, neurodegenerative disease characterized by loss of function and death of nerve cells in several areas of the brain leading to loss of cognitive function such as memory and language. "Studies have reported that sleep loss can reduce the expression of the core clock gene Bmal1 in the pineal gland, thereby aggravating the Alzheimer’s disease neuropathology." (PMID 38907352, 2024). "For example, in Alzheimer’s disease, the loss of daily rhythmic patterns that modify the expression of the BMAL1 gene correlates with an increased segregation of the TAU protein, more significant cognitive impairment, and nocturnal awakenings." (PMID 38673986, 2024). "For example, changes in rhythmicity of the clock gene basic helix-loop-helix ARNT like 1 (Bmal1) have been observed in the early stages of Alzheimer disease (AD) patients." (PMID 38565934, 2024). "We then examined expression of genes involved in the circadian clock, the BMAL1 aKO astrocyte activation phenotype, and Alzheimer’s Disease." (PMID 35110643, 2022). "In summary, our results demonstrate that elevated CLOCK and BMAL1 induce the dysfunction and cytotoxicity of astrocytes via the impairment of aerobic glycolysis in Alzheimer’s disease." (PMID 33114015, 2020). "Recently, it has been shown that the intrinsic circadian clocks, such as REV-ERBα, REV-ERBβ, and Bmal1, affect microglial amyloid-β clearance in the 5XFAD mouse model of Alzheimer’s disease." (PMID 33363534, 2020). "Some proteins, such as Aβ present in Alzheimer’s disease, alter the expression of PER1 and PER2 in the SCN, and the degradation of BMAL1, deregulating the circadian rhythm." (PMID 38673986, 2024). "Diminished BMAL1 and REV-ERBα expression have also been described in mouse models of Alzheimer’s disease (AD)." (PMID 33258449, 2020). "Similarly, the rhythmic expression of specific sleep genes (BMAL1, CRY1, and PER1) is also found to be disturbed in neurodegenerations such as mild cognitive impairment (MCI) and Alzheimer’s disease (AD) dementia." (PMID 35052403, 2021). "Because adenosine absorption is regulated by BMAL1 whose expression oscillates as a function of time‐of‐day in the intestine, it is of interest to examine potential time‐of‐day effects on cognition of adenosine supplementation using 5 × FAD mouse model of Alzheimer's disease (AD)." (PMID 40539410, 2025).
colitis (18 papers, 2018 to 2025). Inflammation of the colon. "In conclusion, we demonstrated that Bmal1 deficiency exacerbated DSS-induced colitis by impairing intestinal barrier function through impaired autophagy." (PMID 38895112, 2024). "Meanwhile, the use of the autophagy agonist rapamycin in vivo attenuates the more severe colitis caused by Bmal1 deficiency through inhibiting IECs apoptosis and enhancing intestinal epithelial barrier function." (PMID 38895112, 2024). "The Ki67 and pHH3 data suggest that daily proliferation rhythms during colitis are present in the epithelium of Bmal1+/+ controls and are suppressed in circadian-deficient Bmal1-/- mutants." (PMID 35223537, 2022). "No changes in goblet cells or crypt abscess scores were found in Bmal1-deficient colitis mice." (PMID 37218867, 2023). "Clock controlled genes are implicated by observations that deletion of Bmal1 in dextran sulfate sodium (DSS)-induced colitis mice delayed colon epithelium regeneration via disruptions to rhythms of cell proliferation suggesting Bmal1 is necessary for UC recovery." (PMID 37711458, 2023). "However, we found that upon DSS treatment, Bmal1 cKO mice exhibited a resistance to DSS-induced colitis, as evidenced by less weight loss, more intact epithelial barrier structure and function, as well as less infiltration of inflammatory factors and immune cells compared to control mice." (PMID 40307620, 2025). "To better assess the role of Bmal1 in intestinal inflammation, we introduced the experimental colitis in control or Bmal1-cKO mice through unrestricted access to 3% DSS solution." (PMID 40307620, 2025). "To further reveal the underlying mechanism by which Bmal1 governs the progression of colitis, we performed bulk RNA sequencing in colonic epithelial cells isolated from control and Bmal1 cKO mice at 7 days post DSS treatment (Dataset EV1)." (PMID 40307620, 2025). "We then investigated the role of Bmal1 in colitis by generating inducible intestinal epithelium-specific Bmal1 knockout (cKO) mice (Villin-CreERT2;Bmal1fl/fl), by intraperitoneal injection of tamoxifen for five consecutive days." (PMID 40307620, 2025). "In the present study, we surprisingly observed that mice in the active circadian phase are more resistant to DSS-induced colitis, and ablation of the circadian gene Bmal1 renders the intestinal epithelium resistance to colitis." (PMID 40307620, 2025). "Surprisingly, different from control mice, Bmal1 cKO mice developed less severity of colitis even treated with DSS at the resting time ZT0." (PMID 40307620, 2025). "This seems to contradict the findings of previous studies showing that mice with global knockout of the circadian genes Bmal1, Per1/2, or Rev-erbβ exhibit more severe symptoms in experimental colitis." (PMID 40307620, 2025). "Collectively, these results indicate that Bmal1 cKO mice exhibited less inflammatory and immune response in colon, thus more resistant to colitis." (PMID 40307620, 2025). "Mice in the active phase are more resistant to DSS-induced colitis, while the circadian regulator BMAL1 activates apoptotic genes to promote colitis." (PMID 40307620, 2025). "Overall, our study highlights the pivotal role of the circadian gene Bmal1 in the regulation of colitis and provides a potential drug target for colitis treatment." (PMID 40307620, 2025). "Mice with an intestinal epithelial-specific knockout of Bmal1 develop more severe colitis in response to dextran sulfate sodium (DSS)." (PMID 41425940, 2025). "Consistently, reducing Bmal1 expression by the REV-ERBα agonist SR9009 has the best therapeutic efficacy against DSS-induced colitis at ZT0." (PMID 40307620, 2025). "We also found that the use of the autophagy agonist rapamycin (DSS: Bmal1-/- + rapamycin group) alleviated colitis exacerbated by Bmal1 knockout." (PMID 38895112, 2024).
colitis (continued). "We found that CRD mice with downregulated Bmal1 expression were more sensitive to DSS-induced colitis and had more severely impaired intestinal barrier function than wild-type mice." (PMID 38895112, 2024). "We then further confirmed the role of the Bmal1–autophagy–gut barrier function axis in the pathogenesis of colitis." (PMID 38895112, 2024). "We assessed the severity of colitis and found that the DSS: Bmal1-/- group showed significantly greater weight loss and a higher DAI score than the DSS: WT group." (PMID 38895112, 2024). "Bmal1-/- mice exhibited more severe colitis, accompanied by decreased tight junction protein levels and increased apoptosis of intestinal epithelial cells compared with wild-type mice, which were alleviated by using the autophagy agonist rapamycin." (PMID 38895112, 2024). "The deletion of Bmal1, a core transcription factor, leads to a complete loss of the circadian rhythm and exacerbates the severity of dextran sodium sulfate (DSS)-induced colitis in mice." (PMID 38895112, 2024). "DSS + UVB light-treated mice showed significantly increased Bmal1-, Clock- and Rev-erbα-mRNA levels and even higher colitis scores than the DSS-only and control groups." (PMID 37218867, 2023). "Bmal1 KO also leads to a lower level of regulatory B cells in the intraepithelial region, which expresses highly programmed death ligand 1 to alleviate colitis severity." (PMID 38089624, 2023). "In contrast to Bmal1−/− mice with colitis, in which epithelial cell proliferation was consistently low, cell proliferation in diseased Bmal1+/+ mice fluctuated throughout the day." (PMID 37218867, 2023). "Nevertheless, Bmal1−/− mutants showed significant morphological abnormalities and increased immune cell infiltration compared to wild-type colitis mice." (PMID 37218867, 2023). "Further, jetlag-induced circadian disruptions in DSS-induced colitis mice aggravated colitis, disrupted rhythms of Clock and Bmal1 expression, and reduced Per2 expression." (PMID 37711458, 2023). "Our data demonstrate that circadian rhythms are a feature of colitis and that the core clock gene, Bmal1, is critical in resolving colitis." (PMID 35223537, 2022). "Both Lcn2 and Reg3g exhibited significantly increased expression in Bmal1+/+ control colon tissue following induction of DSS-colitis." (PMID 35223537, 2022). "The disease activity of colitis was found to exhibit time-dependent variation in Bmal1+/+ control mice but is constant and elevated in Bmal1-/- mutants, who exhibit poor recovery." (PMID 35223537, 2022). "During colitis, circadian clock activity is present in the epithelial and blood cells of Bmal1+/+ controls although the rhythms have lower amplitude, meaning that the rhythms are weaker in their transcriptional strength and thus functional output." (PMID 35223537, 2022). "This is also apparent upon DSS-induced colitis where the expression of Hopx and Lgr5 remains higher in the morphologically intact proliferating crypts of Bmal1+/+ controls at 6 days but is decreased in Bmal1-/- mutant animals." (PMID 35223537, 2022). "An increase in average muscle thickness is also present in Bmal1-/- colon tissue following 10 days of recovery, similar to that noted during colitis." (PMID 35223537, 2022). "Since increased barrier permeability plays an important role in IBD, we stained for Cldn1 in Bmal1+/+ controls and Bmal1-/- mutant tissue with colitis." (PMID 35223537, 2022). "Our data using the Bmal1-/- mutant are consistent with a recent study that found DSS-induced colitis is increased in severity in a different Bmal1 mutant mouse strain, with higher disease scores and poor recovery compared to controls." (PMID 35223537, 2022). "We have built from these findings and determined that in addition to affecting colitis progression, Bmal1 promotes the regeneration of the colonic epithelium." (PMID 35223537, 2022).